SEMA3A (semaphorin 3A)
Diseases named in the same sentence as SEMA3A in open-access papers (continued):
Sharing a sentence is not in itself a finding about the gene and the disease.
glioma (continued). "The release of VEGFA and semaphorin 3A (Sema 3A) by tumor cells, including glioma, further activates NRP1, triggering the activation of VEGFR1 and subsequent recruitment of TAMs in glioma." (PMID 39033204, 2024). "The expression levels of Sema3A and NRP1 strongly correlated with tumor grades, and they were significantly higher in GBMs compared with low-grade gliomas (LGGs)." (PMID 37788099, 2023). "To evaluate the potential correlation between the expression levels of the Sema3A/NRP1 axis components with tumor grade and survival, we interrogated TCGA clinical glioma data sets." (PMID 37788099, 2023). "The RTK ligands including EFNB2, SEMA3D, PDGFA, SEMA3A and FGF14 were amplified in ~5% of the RMPAhigh gliomas." (PMID 27385209, 2016). "The mechanism of EGCG+HC may be through the downregulation of SEMA3A and SEMA3F transcript expression which may play some roles in inhibiting the glioma proliferation and halts invasion via Plexin A1 (PLXNA1) and B2 (PLXNB2) receptors." (PMID 35392560, 2022). "Since Sema3A-neuropilin signaling demonstrated positive effects on cell proliferation in glioma and glioblastoma and negative effect on cell proliferation in breast cancer, its effects may depend on cell context." (PMID 30862786, 2019). "However, more recently Sema3a has been found to bind to COS cells expressing Nrp2 (albeit 1.3 fold less than Nrp1 expressing COS cells), and a functional blocking antibody against Nrp2 removes the chemorepulsive effect of Sema3a on at least one human glioma cell line in vitro." (PMID 22783168, 2012). "For the other studied genes (SEMA3A, B, C, E, F, G, NRP1, NRP2 and SEMA4D), we did not observe statistical difference between low- and high-grade gliomas." (PMID 18781179, 2008).
rheumatoid arthritis (18 papers, 2012 to 2025). A chronic, systemic autoimmune disorder characterized by inflammation in the synovial membranes and articular surfaces. "In patients with systemic lupus erythematosus reduced expression of SEMA3A correlated with inflammation and disease severity, and exogenous administration of SEMA3A was associated with markedly reduced articular inflammation in the rheumatoid arthritis mouse model." (PMID 36551769, 2022). "The transient ligation of sema3A on Tregs from patients suffering from rheumatoid arthritis (RA) is decreased in association with increased disease activity." (PMID 30967873, 2019). "Serum SEMA3A levels were decreased in SLE while increased in rheumatoid arthritis and Sjogren’s syndrome, compared to healthy controls." (PMID 37835781, 2023). "Serum SEMA3A was decreased in patients with systemic lupus erythematosus (SLE) and was increased in patients with rheumatoid arthritis and Sjogren’s syndrome, suggesting the important role of SEMA3A in immune-related diseases." (PMID 37835781, 2023). "In patients with autoimmune diseases (e.g., SLE, rheumatoid arthritis, systemic sclerosis and allergic diseases), a reduced expression of SEMA3A correlated with T-cell-mediated inflammation and disease severity." (PMID 37893159, 2023). "On the other hand, SEMA3A has been shown to promote the apoptosis of fibroblast-like synoviocytes and thus obstructs osteoclastogenesis in rheumatoid arthritis." (PMID 34821196, 2021). "The importance of SEMA3A in autoimmune disorders is highlighted by the finding of reduced expression of SEMA3A in patients with rheumatoid arthritis and SLE that correlates with T-cell mediated inflammation and disease severity." (PMID 30592759, 2018). "Actually, decreased levels of SEMA3A were observed in synovial tissues from rheumatoid arthritis patients compared to synovial tissues in OA patients, and the reduction of SEMA3A expression has been correlated with rheumatoid arthritis exacerbation." (PMID 30375409, 2018). "The aim of this study was to evaluate the serum levels of Sema3A and Sema4D and to investigate their clinical significance in rheumatoid arthritis (RA)." (PMID 30538782, 2018). "The injection of sema3A into a mice model of rheumatoid arthritis was proven to be highly beneficial, both in attenuating clinical symptoms and in decreasing inflammatory mechanisms." (PMID 29670620, 2018). "A recent study revealed that Sema3A expression was downregulated in rheumatoid arthritis and inflammatory bowel disease, which was in accordance with our results." (PMID 29457037, 2017). "Sema3A has been reported to be a potential candidate to treat experimental rheumatoid arthritis and different types of cancer through modulation of angiogenesis, cell proliferation, migration and adhesion." (PMID 27791986, 2016). "The study by Catalano was the first to report on the defective expression of sema3A in CD4 T cells derived from patients with rheumatoid arthritis (RA)." (PMID 22697500, 2012). "That is shown in the research of Sema3A expression on Treg, serum levels of Sema3A, and tissue expression of Sema3A in bowel biopsies from patients with bowel diseases, on mouse models of rheumatoid arthritis and the cells from SLE patients." (PMID 38139064, 2023). "In this respect, we aim to investigate how Sema3A affects key metabolic pathways in T cells during homeostasis and rheumatoid arthritis (RA), and on the AKT/mTORC1 signaling axis." (PMID 41303643, 2025). "The effect and mechanisms of Sema3A action in rheumatoid arthritis (RA) has been examined in vitro using PBMC derived from RA patients and in vivo in a mouse model of collagen-induced arthritis (CIA)." (PMID 30134791, 2018). "Hence, it was reported that SEMA3A is involved in the pathogenesis of autoimmune diseases, including SLE, rheumatoid arthritis and Sjogren’s syndrome." (PMID 37835781, 2023).
rheumatoid arthritis (continued). "Therefore, Sema3A has recently been recognized as a new paradigm in the pathogenesis of autoimmune diseases such as systemic lupus erythematosus (SLE), rheumatoid arthritis (RA) and multiple sclerosis (MS)." (PMID 38139064, 2023).
glioblastoma (16 papers, 2012 to 2025). The most malignant astrocytic tumor (WHO grade IV). "Prior research has shown that Semaphorin 3A (SEMA3A), which is known for its axon guidance and antiangiogenic properties, has been implicated in glioblastoma development." (PMID 35392560, 2022). "For example SEMA3D and SEMA3E displayed strong inhibitory effect on the glioblastoma cells whereas SEMA3A and SEMA3B expression just caused persistent cell shape contraction." (PMID 25961819, 2015). "However, there are certain cancers, like prostate cancer, glioblastoma, or pancreatic cancer, where overexpression of SEMA3A is associated with a poor prognosis and the development of metastases." (PMID 38263416, 2024). "In a glioblastoma model, treatment with anti-SEMA3A F11 antibody exhibited a notable tumor inhibitory effect and TAM infiltration in vivo." (PMID 34209679, 2021). "Sdf1, Sema3A and Sema3F are involved in melanoma, multiple myeloma, glioblastoma, neuroblastoma, pancreatic, prostate, ovarian and lung cancers." (PMID 30944331, 2019). "The availability of BA‐induced oxidative stress and SEMA3A biomarkers in a dose‐dependent manner, the mechanism of apoptosis, and the effective dose of BA can be evaluated for the focus of future pre‐clinical studies on glioblastoma." (PMID 40318008, 2025). "Sema3A was also observed to promote, rather that inhibit, glioblastoma progression through the induction of tumor cells proliferation and macrophages recruitment and treatment with an anti-semaphorin-3A antibody inhibited the progression of glioblastoma tumors in mouse models." (PMID 30696103, 2019). "Sema3A promotes glioblastoma cell dispersal but inhibits angiogenesis in meningiomas." (PMID 23050142, 2012). "In terms of glioblastoma (GBM), the expression of Sema3A is significantly higher in tumor tissues relative to adjacent normal tissues." (PMID 35155237, 2022). "It was demonstrated that expression of SEMA3A, SEMA3D, and SEMA3F proteins significantly inhibited angiogenesis process and the formation of subcutaneous tumors derived from glioblastoma cells U87MG." (PMID 33036421, 2020). "Furthermore, in glioblastoma multiforme and in pancreatic cancer, sema3A promotes rather than inhibits metastatic dissemination." (PMID 30696103, 2019).
prostate carcinoma (16 papers, 2015 to 2025). A carcinoma that arises from epithelial cells of the prostate gland. "On the contrary, in pancreatic cancer and prostate cancer, SEMA3A overexpression has been found and it could be linked to metastatic progression." (PMID 38263416, 2024). "The Perlecan-Semaphorin 3A-Plexin A1-Neuropilin-1 (PSPN) Complex at the cell surface of prostate cancer (PCa) cells influences cell–cell cohesion and dyscohesion." (PMID 33809984, 2021). "For instance, Sema3A inhibits tumor growth, migration, and metastasis of breast and prostate cancer cells as well as melanoma but facilitates pancreatic and colon cancer cell invasion." (PMID 28182100, 2017). "Sema3A/B/C/E are also involved in the lymph node metastasis of prostate cancer, but they are likely to modulate the behavior of prostate cancer with a pro-tumor or anti-tumor effect, depending on the subtype." (PMID 25961819, 2015). "The authors reported up-regulation of Sema3C and downregulation of Sema3A and Sema3E levels after exposure to hypoxia or hypoxic mimetic agents, thus suggesting a different role of Sema3 family members in the progression of prostate cancer." (PMID 33858502, 2021). "Previous studies have shown that Sema3A inhibits angiogenesis in prostate cancer." (PMID 28683823, 2017). "Inhibition of HIF-1α suppressed prostate cancer, Evodiamine impairs HIF-1α histone lactylation to inhibit Sema3A-mediated angiogenesis and PD-L1 by inducing prostate cancer cell ferroptosis." (PMID 40535811, 2025). "Furthermore, evodiamine, a natural alkaloid, has been shown to inhibit lactate-induced histone lactylation, increase Sema3A expression, and reduce angiogenesis, evodiamine could be a promising candidate for prostate cancer therapy, providing a metabolic-epigenetic approach to overcoming resistance." (PMID 40535811, 2025). "In prostate cancer cells, lactate treatment boosted the expressions of hypoxia-inducible factor-1α (HIF-1α) and PD-L1 while concurrently reducing Sema3A expression." (PMID 39690423, 2024). "In direct conflict to this, reports have also shown Sema3A signaling to reduce cell adhesion to the ECM, and to impair the invasiveness of both breast and prostate cancer cells in vitro." (PMID 36970722, 2022). "Furthermore, evodiamine significantly suppressed lactate-induced angiogenesis in prostate cancer cells by limiting histone lactylation and HIF-1α expression, which improved Sema3A transcription while downregulating PD-L1 transcription." (PMID 39690423, 2024). "In contrast, it was reported that perlecan interacts with a complex of sema3A, plexin-A1, and NRP-1 on the cell surface of prostate cancer cells and that cleavage of this complex by MMP-7 cell-cell bonds promotes the metastatic dissemination of prostate cancer cells." (PMID 37627074, 2023). "In prostate cancer cells, HRE sequences have been found in the promoter of Sema3A, Sema3B, Sema3C, Sema3E, and Sema3F genes, but not in Sema3D." (PMID 33858502, 2021).
systemic lupus erythematosus (15 papers, 2012 to 2025). An autoimmune multi-organ disease typically associated with vasculopathy and autoantibody production. "Semaphorin3A (sema3A), a unique regulatory master of the immune system, was shown to be decreased in the serum of systemic lupus erythematosus (SLE) patients, in association with disease severity." (PMID 36703747, 2022). "Emerging evidence suggests that Sema3A regulates B and T lymphocytes and contributes to the progression and development of diseases such as Systemic Lupus Erythematosus and cancer." (PMID 34039431, 2021). "With this in mind, we further reported that serum levels of sema3A were significantly lower in patients with systemic lupus erythematosus when compared to that in normal individuals." (PMID 25978359, 2015). "In addition, it has also been reported that SEMA3A can be a predictive biomarker for ankylosing spondylitis and systemic lupus erythematosus, suggesting the effect of SEMA3A signaling on the regulation of the immune system." (PMID 32521824, 2020). "In addition, Sema3A levels negatively correlate with the Systemic Lupus Erythematosus Disease Activity Index (SLADAI), and lower serum levels of Sema3A are associated with kidney involvement and presence of anti-cardiolipin antibodies, which are risk markers for thrombotic events in SLE patients." (PMID 30654587, 2019). "The concentration of sema3A was found to be reduced in serum of systemic lupus erythematosus (SLE) patients and in correlation with SLE disease activity." (PMID 30967873, 2019). "Several studies have indicated that a reduction of Sema3A expression is involved in the exacerbation of autoimmune diseases, such as RA and systemic lupus erythematosus (SLE)." (PMID 23343469, 2013). "This study was undertaken to evaluate the role of sema3A and NP-1 in the pathogenesis of systemic lupus erythematosus (SLE) and the specific effect of sema3A on the auto-reactive properties of B cells in SLE patients." (PMID 22697500, 2012). "Therole and alteration in the level of SEMA3A have beeninvestigated in some autoimmune diseases, includingsystemic lupus erythematosus (SLE), rheumatoidarthritis (RA), psoriasis and systemic sclerosis (SSc).In some of these studies, down-regulation of SEMA3Ahave been reported." (PMID 29308627, 2018). "Sema3A is another immune semaphorin that acts as a negative regulator of lymphocytic function in the pathogenesis of several autoimmune diseases, such as systemic lupus erythematosus and systemic sclerosis." (PMID 30538782, 2018).
osteoporosis (14 papers, 2015 to 2025). A condition of reduced bone mass, with decreased cortical thickness and a decrease in the number and size of the trabeculae of cancellous bone (but normal chemical composition), resulting in increased fracture incidence. "Its multifaceted role in countering skeletal fragility and mitigating bone loss positions Sema3A as a promising candidate for further exploration in the context of therapeutic interventions for osteoporosis." (PMID 38078001, 2023). "It has been proven that Plexin-A2, which functions as an auxiliary receptor to identify Sema3A, has a diversity of gene loci linked to osteoporosis and osteoporotic fractures." (PMID 38078001, 2023). "Radiation therapy or spaceflight radiation promotes osteoclast differentiation and causes increased bone loss and an elevated risk of osteoporosis, and Sema3a plays an important role in bone remodeling regulation." (PMID 29975739, 2018). "In light of these compelling findings, it becomes apparent that Sema3A may be intricately linked to the risk factors and pathogenesis of osteoporosis." (PMID 38078001, 2023). "Moreover, sema3a has been demonstrated to be a target to treat osteoporosis and the recombinant sema3a protein administration decreases bone loss in an ovariectomized mouse model." (PMID 31481931, 2019). "Sema3A, a substance linked to bone homeostasis, might play a role in the control of osteoporosis." (PMID 38078001, 2023). "In our study, the decreased serum Sema3A level was more often observed in people with osteoporosis or individuals with low bone mass, especially in male patients." (PMID 35250478, 2022). "Sema3A has a good curative effect on the osteoporosis model, the cortical bone defect model, and the rat osteoporotic fracture model, which can promote bone regeneration, increase bone mass, and reduce bone loss in injured parts." (PMID 31467560, 2019). "Nowadays, sema3a is suggested to work in the development of diabetes, diabetic complication and osteoporosis." (PMID 31481931, 2019). "Elucidation of this mechanism not only reveals a new pathway for the superior osteogenic effects of S-EXOs@BMSC but also offers a foundational theory for developing therapies targeting the Sema3A signaling pathway for managing osteoporosis and other conditions affecting bones." (PMID 41144380, 2025). "Also, the Sema3A/neuropilin axis exhibits an osteoprotective function and mitigates the pathologies of bone fracture healing and osteoporosis." (PMID 35250478, 2022). "This study aimed to explore the associations of genetic variants in the semaphorin 3A (SEMA3A) signaling pathway genes, including SEMA3A, NRP1, PLXNA1, PLXNA2 and PLXNA3 with osteoporosis (OP) risk and bone mineral density (BMD) in a Chinese Han older adult population." (PMID 36425469, 2022). "Moreover, patients with osteoporosis (T-score < −2.5) or low bone mass (T-score between −2.5 and −1) had lower serum Sema3A levels compared to the normal BMD group." (PMID 35250478, 2022). "Sema3a promoted Raw264.7 cell apoptosis after irradiation, indicating that Sema3a could be a potential therapeutic target for radiation-induced osteoporosis." (PMID 29975739, 2018). "Naringin could increase the expression of Sema3A and the activation of Wnt/β-catenin signalling to prevent disuse osteoporosis induced by denervation." (PMID 27109829, 2016). "In conclusion, the osteoprotective role against disuse osteoporosis of naringin may be mediated as follows: 1) Naringin promotes the secretion of Sema3A by osteoblasts and osteocytes." (PMID 27109829, 2016). "For example, the recent finding that Sema3A acts as a biological regulator of bone homeostasis, able both to reduce bone resorption and increase bone synthesis, is of potential importance for the development of therapeutics to combat osteoporosis." (PMID 25624520, 2015).
osteoporosis (continued). "Furthermore, local injection of Sema3A into a rat model of osteoporosis has been found to significantly increase callus size and bone density after bone injury, enhance calcium salt deposition and support functional remodelling of the callus 2 months after fracture." (PMID 38568078, 2024). "Therefore, regulation of Sema3A and its corresponding signaling pathway may be helpful for treatment of osteoporosis." (PMID 27803667, 2016). "In addition, decreased Sema3A is correlated with the development of disuse osteoporosis." (PMID 27109829, 2016). "This was reconfirmed by in vivo experiments in which OVX mice were used to establish an osteoporosis model, and OVX decreased Sema3A expression in bone tissue." (PMID 38078001, 2023). "Our studies suggest that the down-regulation of Sema3A and the subsequent inactivation of Wnt/β-catenin signalling may be some of the mechanisms involved in USN-induced osteoporosis." (PMID 27109829, 2016). "The present study explores whether naringin can prevent disuse osteoporosis induced by unilateral sciatic neurectomy (USN) and whether the Semaphorin 3A-induced Wnt/β-catenin signalling pathway is involved in the osteoprotection of naringin." (PMID 27109829, 2016).